IL17A (interleukin 17A)
Diseases named in the same sentence as IL17A in open-access papers (continued):
Sharing a sentence is not in itself a finding about the gene and the disease.
colorectal cancer (continued). "Finally, the immune checkpoints PDCD1 (PD-1) and CD274 (PDL-1) were also positively correlated with interleukin-17A mRNA expression, indicating that interleukin-17A is a promising predictor of the immunotherapeutic outcome of PD-1/PDL-1 blockade in colorectal cancer." (PMID 36098359, 2022). "Likewise, in right-sided colorectal cancer, the abnormal activation of phospholipase a2-IVa/arachidonic signaling induced the generation of CD39+γδ Treg cells, which mediated immunosuppressive effects via the secretion of IL-17A and adenosine." (PMID 35948909, 2022). "To date, only one team reported that high IL-17A expression, compared to expression in adenoma and non-tumor tissue, is an independent favorable prognostic factor that predicts overall survival of colorectal cancer by quantifying RNA expression in tissues and IL-17A immunohistochemical levels." (PMID 28347290, 2017). "The role of IL‐17A in lung cancer treated with ICI is still not largely unknown, but a study showed that IL‐17A can increase the expression of PD‐L1 in colorectal cancer treated with anti‐PD‐1 therapy via p65/NRF1/miR‐15b‐5p and promotes the resistance of anti‐PD‐1 thearpy." (PMID 37062076, 2023).
viral infection (245 papers, 2010 to 2026). "The character of IL-17 during viral infections remains controversial, as IL-17A can be protective or pathogenic, depending on specific circumstances." (PMID 39431236, 2024). "In terms of viral infections, IL-17A plays both protective and pathogenic roles." (PMID 40632810, 2025). "In addition, the production of inflammatory chemokines normally triggered by IL-13 and IL-17A, which are strongly linked to not only viral infection but also asthmatic condition, was reduced by the late addition of BUD." (PMID 32120846, 2020). "In addition, the production of inflammatory chemokines that were induced by not only viral infection, but also two cytokines strongly linked to asthmatic conditions, IL-13 and IL-17A, were reduced by BUD." (PMID 32120846, 2020). "Taken together, our data suggest that IL-17A may be associated with the pathogenesis of viral-infection-triggered exacerbation by promoting release of neutrophil chemoattractants from bronchial epithelial cells." (PMID 26505478, 2015). "During other viral infections, IL-17A was found to be crucial for priming hepatic CD8+ T cells in adenovirus-infected mice and partly responsible for the clustering and activation of CD8+ T cells in the spleen following vaccinia virus infection." (PMID 40632810, 2025). "In regard to viral infection, IL-17A signaling in B-1a cells promotes natural antibody production during pulmonary influenza infection." (PMID 41335125, 2025). "Chronic inflammation, triggered by factors such as viral infections, oxidative stress, and metabolic dysregulation, leads to the persistent activation of pro-inflammatory cytokines, including IL-1β, IL-17A, and TGF-β." (PMID 40607394, 2025). "Elevated levels of IL-6, INF-g, TNF-a, and IL17a mark an exacerbated inflammatory response and reflect the body’s attempt to combat the viral infection, with IL-6 being a pivotal mediator of fever and acute phase reactions." (PMID 39203987, 2024). "Taken together, these results demonstrate the important role of γδ T17 cell production of IL-17A in protecting the host from early viral infection." (PMID 39504049, 2024). "In fact, the functional role of IL-17A is much more understood in bacterial infections, while little or much less is known about its role in viral infection." (PMID 37631976, 2023). "It is also worth mentioning that IL-17A play a role in induce protective inflammatory responses, hindering viral infection." (PMID 36993968, 2023). "As such, during early infection, IL-17A can antagonize Th1 activity while promoting productive MHV68 viral infection." (PMID 37631976, 2023). "In viral infection models, IL-17A overexpression modulates Th1/Th2 responses, leading to exacerbation of vaccinia virus virulence in infected mice." (PMID 37631976, 2023). "Specifically, IL-17A (secreted from unconventional T cells) forms NETs to clear the virus in the early stages of viral infection, thereby protecting the host." (PMID 38029108, 2023). "An alternative mechanism of activation of NKG2D+IL-17a+ γδ T cells is by endogenous lipids presented by B-1a cells during viral infection." (PMID 37744375, 2023). "Mechanistically, host cell-released lipids during viral infection are presented by lung infiltrating CD1d+ B-1a cells to activate IL-17A production in γδ T cells via γδTCR-mediated IRF4-dependent transcription." (PMID 33772013, 2021). "Consistently, B-1a depletion resulted in significantly reduced IL-17A production in γδ T cells when compared with control mice upon viral infection." (PMID 33772013, 2021). "We have previously published that the pneumonitis and fibrosis seen in BMT mice in response to viral infection are IL-17A dependent." (PMID 33491663, 2021). "Although the blockade of IL-17A signaling alleviates tissue damage and inflammation during virus infection in murine models, targeting IL-17A alone has limited efficacy in repairing the tissue damage caused by influenza A virus infection." (PMID 34504501, 2021).
viral infection (continued). "To test if IL-17A also inhibits the expression of Ifn-α2 during other virus infections, we infected NIH3T3 cells with West Nile virus (WNV) or Zika virus (ZIKV) in the presence of rIL-17A, and measured Ifn-α2 mRNA by QPCR or ELISA." (PMID 33304351, 2020). "This work uncovered the differential responses of cells infected with two H1N1 IAV strains and the potential roles of IL-17A in modulating virus infection." (PMID 31681209, 2019). "IL-17A is considered to be an important cytokine central to innate and adaptive immune responses to bacterial, fungal, and many viral infections." (PMID 31061831, 2019). "Recently, it has been shown that interleukin 17A (IL-17A) promotes B1-cell infiltration into lungs during viral infection, where B1a cells differentiate into IgM-producing plasma cells." (PMID 30090624, 2018). "For host defense, IL-17A/IL-17A receptor complex is important, since IL-17A is commonly produced during viral infection." (PMID 30134914, 2018). "We further found that γδ T cells prominently expressed IL-22 as well as IL-17A in the liver after viral infection." (PMID 28634408, 2017). "By producing IL-17A to recruit neutrophils and enhance adaptive immunity, IL-17A-producing γδT (γδT-17) cells have an important role in host defence against bacterial, fungal and viral infections, as well as stress, tumour surveillance and autoimmune diseases." (PMID 28067223, 2017). "In conclusion, IL-17A appears to be involved in the pathogenesis of chronic inflammatory airway disease exacerbation, due to viral infection by promoting release of neutrophil chemoattractants from bronchial epithelial cells." (PMID 26505478, 2015). "Mice received either an IL-17A neutralizing antibody or an isotype control antibody one day before and two days after the viral infection." (PMID 24918427, 2014). "To shorten the duration of intervention and thereby reducing the risk of prolonged or secondary infections, we treated mice directly before and during the viral infection with anti-IL-17A or IL-1Ra." (PMID 24918427, 2014). "Treatment with the IL-1Ra, anakinra, proved efficient in reducing neutrophilic inflammation at the peak of viral replication while blocking of IL-17A abrogated neutrophilia in the early phase of viral infection." (PMID 24918427, 2014). "In the present study, we employed Poly I:C to emulate viral infection and examined the effect IL-17A on NK cell-mediated liver injury." (PMID 24069246, 2013). "The role of IL-17A signaling in viral infections is less understood." (PMID 41335125, 2025). "In the case of acute viral diseases, IL-17A, on the one hand, can sensitize antigen-specific effector T cells, promoting the elimination of the agent, on the other hand, an exhaustive IL-17A and IL-6 response can promote viral persistence." (PMID 34211477, 2021). "The roles of IL-17A in inducing appropriate immune responses against viral infections are controversial, IL-17 may play a positive role in antiviral immune responses in several diseases." (PMID 33435966, 2021). "In light of these findings, it would be of interest to study whether simultaneously targeting IL-22 and IL-17A could be a potential approach for virus infection therapy." (PMID 34504501, 2021). "During viral infections, IL‐17A derived from activated lung γδT cells inhibits virus replication." (PMID 31903715, 2020). "IL-17A in viral infections may contribute to secondary inflammatory injury recruiting neutrophils and lymphocytes, and its levels have been found to be elevated in patients with severe COVID-19 pneumonia." (PMID 33276686, 2020). "In addition, IL‐17A has been recently shown to be an important immune modulator during viral infections." (PMID 31777067, 2020). "These pathobionts augment the severity of virus infections by suppression of anti-inflammatory cytokines, T regulatory cells, and B lymphocytes immunoglobulins production and enhance proinflammatory cytokines comprised of IL-17A and IFN-γ production." (PMID 31349568, 2019).
viral infection (continued). "In the cases of bacterial and viral infections and bleomycin toxicity, an IL-1- and IL-17A-associated mechanism is activated to propagate the TGF-β1 pathway, forming an IL-1–IL-17–TGF-β1 axis that serves as a major driver of fibrosis during sustained type 1- and Th17-driven inflammatory responses." (PMID 29872441, 2018). "One can speculate that the segregation of IL-17A is changed at some stage of viral infection and tumor development." (PMID 25990808, 2015). "The lack of difference in viral load between vaccinated mice treated with either anti-IL-17A or control antibody was not expected given the dramatic difference in weight loss between both groups following viral infection." (PMID 24465206, 2014). "However, some studies have reported an enhanced level of IL-17A in other viral infections but as far as we know this is the first reported in OBI." (PMID 22308123, 2010). "Therefore, we hypothesized that IL-17A plays an important role in the pathogenesis of acute exacerbation, due to viral infection in chronic inflammatory airway disease, through interaction with TLR3 signaling." (PMID 26505478, 2015). "Therefore, we hypothesized that IL-17A was involved in the pathogenesis of acute exacerbation, due to viral infection in chronic inflammatory airway diseases." (PMID 26505478, 2015). "Thus,we revealed the pathological role of IL-17A and γδT cells in Poly I:C-induced acute hepatitis, which provides novel insights into viral infection-induced hepatitis and may serve as potential target in clinic immunotherapy against these diseases." (PMID 24069246, 2013). "Further, levels of IL-17A in patients hospitalized with viral infections, including SARS-CoV2 or MERS, increase 3-–20-fold over baseline levels and can exceed the EC50 for the erythroid stimulatory effect of IL-17A in vitro (2 ng/mL)." (PMID 41379768, 2025). "A previous study demonstrated that natural killer cell activity can be inhibited by IL-17A through SOCS3, which can interfere with tumorigenesis and viral infection." (PMID 35296090, 2022). "Differences between samples from controls and neonates with ongoing viral infection in several molecules (filaggrin, VEGF, RANTES (CCL5), HIF-1α, IL-17A and IL-1 β) were also observed, indicating an immune response associated with viral infection." (PMID 36482106, 2022). "Firstly, It has been suggested that IL-17A induces TNF-α and IL-6 expression; therefore, we measured the TNF-α and IL-6 protein levels on the day 7, 60 and 90 post viral infection in the blood." (PMID 23977238, 2013). "Finally, our findings demonstrated a pathological role of IL-17A and γδT cells in Poly I:C-induced acute hepatitis, which provides novel insights into viral infection-induced hepatitis and may serve as potential target in clinic immunotherapy against these disease." (PMID 24069246, 2013). "IL-2, IL-6, IL-17A, and IFN-γ are common immune factors in viral infections." (PMID 40872344, 2025). "The increase in il17a transcript in WT mice infected by VACV was almost completely ablated in VACV-infected TCRδ−/− mice, indicating that γδ T cells, directly or indirectly, are likely responsible for almost all IL-17A production upon virus infection." (PMID 38543790, 2024). "However, in other viral infections like HIV-1 and Hepatitis C, IL-17A has been shown to promote T-cell mediated anti-viral responses through activation and recruitment of dendritic cells, monocytes and neutrophils." (PMID 33499880, 2021). "Collectively, these results suggest a novel function of IL-17A in inhibiting IFN-α2–mediated antiviral responses during CHIKV infection, which may have broad implications in viral infections and other inflammatory diseases." (PMID 33304351, 2020).
viral infection (continued). "Interleukins such as IL17A and IL22, which were upregulated at 3 dpi, are important to maintain mucosal immunity against virus infection and include induction of antiviral proteins, recruitment of neutrophils to infected areas and enhancement of mucosal barrier repair." (PMID 33110122, 2020). "Furthermore, given that IL-17A was able to restore CD8+ T cell dysfunction in treated hosts, targeting the IL-17R pathway not only can help to control viral infections but also can help to fight against other microbes and, eventually, tumors." (PMID 32398312, 2020). "As with IL-17A neutrophil depletion, neutrophil depletion coupled with recombinant viral infection significantly reduced viral dissemination but did not return viral burden to WT MCMV levels." (PMID 31239384, 2019). "During viral infection, IL-17A was also enhanced in PCLS isolated from non-sensitized mice, however, it remained at a baseline in lung tissue derived from HDM-sensitized mice." (PMID 31640701, 2019). "IL-1β driven neutrophilia was mediated by IL-17A in the initial phase of viral infection, but became independent of IL-17A during the peak phase of viral replication." (PMID 24918427, 2014). "Our studies suggest that early immune responses mediated by cells producing IL-17A and IFN-γ resulted in more rapid resolution of the viral infection and may have mitigated against the progressive cytokine release and tissue pathology that occurs with more robust adaptive immune responses." (PMID 32958614, 2020). "To confirm the inhibitory effect of Ad-IL-17AR:Fc, we demonstrated that the myocardial IL-17A protein was reduced significantly in Ad-IL-17AR:Fc- compared with Ad-null-treated mice on day 90 post viral infection; however, Ad-IL-17AR:Fc did not alter the IL-17A receptor expression in the heart." (PMID 23977238, 2013). "While previous studies have demonstrated that IL-17A signaling directly induces CXCL10 production in esophageal cell lines, and the production of IL-17F is necessary for CXCL10 expression in hepatic viral infection models, whether the IL-17 axis induces CXCL10 during NAFLD remains undefined." (PMID 26895034, 2016).
Sepsis (243 papers, 2008 to 2026). Sepsis is defined as life-threatening organ dysfunction caused by a dysregulated host response to infection. "The present findings collectively indicate a potential association between IL-17A and the progression of both sepsis and relapsed B-ALL." (PMID 41007866, 2025). "Neutrophil extracellular traps (NETs) induce IL-17A, which causes harm in some diseases, but this pathway is poorly understood in sepsis." (PMID 41041553, 2025). "First, low concentrations of IL17a have been reported as a good predictor for mortality in sepsis caused by distinct pathogens." (PMID 36969221, 2023). "We utilized IL-17A-deficient mice to investigate the role of IL-17A-producing γδ T cells in sepsis using the cecum ligation and puncture (CLP) model." (PMID 37475963, 2023). "ITK inhibitor-treated mice with sepsis show attenuated IL-17A signaling, which is associated with the upregulation of IL-10/Nrf2 signaling and the amelioration of depression-like symptoms in mice." (PMID 37175808, 2023). "IL-17A has been found in several other studies in association to sepsis severity and mortality but had a moderate contribution in our prediction models." (PMID 37691028, 2023). "Lnc‐GAS5 did not relate to Th1 cells (p = 0.059) or IFN‐γ (p = 0.192); while negatively linked with Th17 cells (p = 0.002) and IL‐17A (p = 0.019) in sepsis patients." (PMID 35325494, 2022). "The current study disclosed that the upregulation of MALT1, Th1 cells, Th17 cells, and IL‐17A was correlated with higher mortality risk in sepsis patients." (PMID 35262976, 2022). "Neutralizing IL-17A in the peritoneum has a protective effect on organ tissue damage and death caused by sepsis." (PMID 36253831, 2022). "Patients with acute lung injury caused by sepsis have been showing consistently high levels of IL-17A." (PMID 36253831, 2022). "The study has shown in cecal ligation and puncture (CLP)-induced sepsis mouse model that IL-17A or IL-17A receptor deficiency significantly increased the mortality, which correlated with reduced neutrophil recruitment and more severe bacteremia." (PMID 33995408, 2021). "In particular, with an extended antibiotic course (LE), this was accompanied by an overall decrease in IL-17A production in the intestine, an increase in baseline bacterial translocation and increased susceptibility to late onset sepsis." (PMID 32737397, 2020). "In humans, serum levels of IL-17 are predictive of the development of sepsis and mortality in poly-trauma patients and mutations in the IL-17A gene are associated with increased susceptibility to infection caused by gram positive bacteria and mortality." (PMID 31507598, 2019). "Neutrophil infiltration is a hallmark of inflammatory injury after sepsis, and one of the main functions of IL-17A is neutrophil recruitment." (PMID 27334720, 2016). "Enhanced IL-17A associated with morphine treatment in our sepsis model prompted us to investigate the role of IL-17A in sepsis progression." (PMID 26039416, 2015). "Using mice genetically deficient of IL-17A, a different conclusion was reached in terms of the role of IL-17A for survival of polymicrobial sepsis." (PMID 23369364, 2012). "To conclude, the IL17A rs1974226 GG genotype is associated with increased numbers of Gram-positive infections and increased 28-day mortality in severe sepsis patients." (PMID 22026963, 2011). "IL17A genetic variation is associated with altered susceptibility to Gram-positive infection and 28-day mortality of severe sepsis." (PMID 22026963, 2011). "We found that the G allele of the IL17A SNP was associated with increased 28-day mortality in both cohorts of severe sepsis/septic shock patients." (PMID 22026963, 2011). "We analyzed whether the polymorphism was correlated with the cytokine expression of IL1β, IFNα2, IFNγ, TNF-α, IL-33, IL12p70, MCP-1, IL-6, IL-10, IL-17a, IL-18, or IL-23 to further investigate the effect of the polymorphism in sepsis patients." (PMID 38338680, 2024).